ROCK2 (Rho associated coiled-coil containing protein kinase 2)
Diseases named in the same sentence as ROCK2 in open-access papers (continued):
Sharing a sentence is not in itself a finding about the gene and the disease.
prostate carcinoma (12 papers, 2012 to 2024). A carcinoma that arises from epithelial cells of the prostate gland. "Overexpression of miR-122 was shown to reduce the proliferation of prostate cancer cells and the expression of ROCK2, although treatment with ROCK2 was found to diminish this effect." (PMID 36803831, 2023). "Targeting the ROCK2 gene, pathways such as autophagy or HR may present an opportunity to reverse acquired resistance and reinforce the effect of PARPi in prostate cancer." (PMID 36010871, 2022). "Consequently, miR-122 may reduce ROCK2 expression, so preventing prostate cancer cells from multiplying." (PMID 36803831, 2023). "We report that RhoBTB1 depletion increases prostate cancer cell invasion and induces elongation in Matrigel, a phenotype similar to that induced by depletion of ROCK1 and ROCK2." (PMID 31431478, 2019). "In prostate cancer, Kroiss and his colleagues also demonstrated that miR-135a decreased prostate cancer cell migration and invasion through downregulating ROCK1 and ROCK2." (PMID 27323416, 2016). "In addition, microRNA‐122 inhibited the cell viability of prostate cancer cells via down-regulating ROCK2, and ROCK1 or ROCK2 knockdown in DU145 or PC-3 cells inhibited cell proliferation." (PMID 39455522, 2024). "Additionally, Kroiss had demonstrated that miR-135a decreased prostate cancer cell migration and invasion through downregulating ROCK1 and ROCK2." (PMID 27323416, 2016).
glioma (11 papers, 2011 to 2024). A benign or malignant brain and spinal cord tumor that arises from glial cells (astrocytes, oligodendrocytes, ependymal cells). "ROCK2 expression was associated with poor overall survival of MGMTlow (MGMT−) recurrent gliomas with TMZ therapy (n = 100), compared with MGMThigh (MGMT+) subset." (PMID 35145081, 2022). "Previous work from our laboratory determined that ROCK2 was the important mediator of acquired resistance to TMZ in glioma cells and the mechanism underlying the regulation of ABCG2, which was functions as a high-capacity drug efflux transporter." (PMID 35145081, 2022). "Rho-associated coiled-coil kinase 2 (ROCK2) is an attractive therapeutic target because it is overexpressed in many malignancies, including glioma." (PMID 24642531, 2014). "In this study, we demonstrated that rho-associated kinase 2 (ROCK2), a cytoskeleton regulator, was highly expressed in MGMTlow recurrent gliomas, and its expression strongly correlated with poor overall survival (OS) time in a subset of MGMTlow recurrent gliomas patients with TMZ therapy." (PMID 35145081, 2022). "In summary, our study revealed that ROCK2 increased HR repair via up-regulating ATM expression in MGMTlow TMZ-resistant glioma cells." (PMID 35145081, 2022). "Fasudil reduces glioma TMZ resistance by inhibiting ROCK2 phosphorylation, thereby inhibiting proliferation." (PMID 37786890, 2022). "MGMTlow recurrent glioma patients with TMZ therapy or TMZ + radiation therapy exhibited an increased level of ROCK2 gene." (PMID 35145081, 2022). "In this study, we generated MGMTlow (or MGMT−) TMZ-R glioma cell lines and demonstrated that ROCK2 inhibition reversed TMZ-resistance in glioma cells via impairment of the DNA repair system." (PMID 35145081, 2022). "And we also found that overactive ROCK2 enhanced homologous recombination repair (HR) in TMZ-resistant (TMZ-R) glioma cell lines with low MGMT expression." (PMID 35145081, 2022). "Levels of RhoA guanosine triphosphate (GTP) were increased and RhoA guanosine diphosphate (GDP) amount was reduced, indicating that RhoA/ROCK2 was activated in TMZ-R glioma cells." (PMID 29416017, 2018). "We have demonstrated that phosphorylation of ROCK2 instead of ROCK1 was increased in our TMZ-R models of glioma." (PMID 29416017, 2018). "In summary, our study revealed that fasudil increased the sensibility of TMZ and reversed TMZ resistance in glioma via the inhibition of ROCK2." (PMID 29416017, 2018). "Major TGF-Beta-EMT inducing factors (RHOA, RAC1, ROCK2, CDC43 and LIMK1) and EMT transcription factors (TWIST1, SOX9, TRIM28 and SERP2) have among the highest risk scores in our glioma transcriptional model." (PMID 28916782, 2017). "Although the cytotoxicity of a ROCK2 inhibitor, namely Fasudil, was previously investigated in glioma cells, to the best of our knowledge, this study provides the first demonstration of the synergistic antitumor effects of siROCK2 with TMZ." (PMID 24642531, 2014). "This suggests the presence of a feedback loop of ROCK expression on RhoA since ROCK1 and ROCK2 are downstream effectors of RhoA in glioma cells." (PMID 24170433, 2014). "Selective knockdown of either ROCK1 or ROCK2 exerted antidromic effects on glioma migration: while ROCK1 deletion altered the substrate-dependent migration, deletion of ROCK2 did not." (PMID 24170433, 2014). "In fact, we revealed that treatment with the ROCK inhibitor Y27632 led to a decrease in MLC-P levels which indicates that ROCK2 is involved in the development of the membrane protrusions occurring in the U343-MG and U373-MG glioma cells with knockdown of SOX2." (PMID 22070920, 2011). "Taken together, these findings demonstrated a strong correlation between ROCK2 and TMZ response in MGMTlow recurrent glioma patients and might suggest a potential role of ROCK2 on TMZ-R." (PMID 35145081, 2022).
glioma (continued). "Interestingly, gene of MGMT was inversely correlated with ROCK2 expression in the recurrent group, especially in the recurrent glioma patient treated with TMZ or TMZ + radiation therapy." (PMID 35145081, 2022). "In this study, we found that ROCK2 was a critical regulator in MGMTlow TMZ-R glioma models." (PMID 35145081, 2022). "Here, we provided evidence that ROCK2 acted redundantly to maintain resistance of TMZ in TMZ-resistant gliomas, and as a ROCK2 phosphorylation inhibitor, fasudil significantly suppressed proliferation of TMZ-resistant gliomas in vivo and vitro via enhancing the chemosensitivity of TMZ." (PMID 29416017, 2018). "Moesin was downstream of ROCK2 and regarded as a glioma progression marker." (PMID 29416017, 2018). "Since we observed that SOX2 depletion led to a decrease in cyclinD1 expression we suggest that the same mechanism might be involved in the increased RhoA/ROCK2 signaling in U343-MG and U373-MG glioma cells." (PMID 22070920, 2011). "Further analysis revealed that the loss of invasive proteolysis-dependent migration capacity of glioma cells with knockdown of SOX2 could be compensated by a shift to amoeboid migration governed by increased RhoA/ROCK2 signaling." (PMID 22070920, 2011). "Herein, we aimed to elucidate whether ROCK2 mediates DNA repair systems in TMZ-resistant gliomas." (PMID 35145081, 2022). "In the present study, we investigated whether the shRNA-induced inhibition of either ROCK1 or ROCK2 alone influences glioma migration and proliferation and elucidated the differences between these two ROCKs in glioblastoma cell migration, substrate preferences, and cell proliferation." (PMID 24170433, 2014). "Subsequently, we further analyzed the previous transcriptome sequencing data and found that silencing PRMT6 in glioma cells can reduce the expression of invasion-related molecules (TGFB1/2, MMP3/9/14, FN1, ROCK2, etc.)." (PMID 39043634, 2024). "Fasudil, a ROCK2 phosphorylation inhibitor, significantly inhibited the proliferation of TMZ‐resistant gliomas." (PMID 37786890, 2022). "Silencing ROCK2 impaired HR repair, and induced double-strand break (DSB) and eradicated TMZ-R glioma cells in culture." (PMID 35145081, 2022). "This study added ROCK2 on the map of relevant molecular changes in TMZ resistance glioma and provided a therapeutic strategy for overcoming TMZ resistance in glioma therapy." (PMID 29416017, 2018). "Our results reveal an indispensable role for ROCK2 and provide strong evidence for the therapeutic use of fasudil in the clinical setting for TMZ-resistant gliomas." (PMID 29416017, 2018). "In contrast, ROCK1 was highly expressed and ROCK2 expression was almost undetectable in three WHO grade III and three WHO grade IV gliomas using immunohistochemistry and western blotting." (PMID 23936026, 2013). "Moreover, the downregulation of ROCK2 combined with TMZ treatment exerted synergistic effects on the induction of apoptosis and the inhibition of cell migration in U251 glioma cells." (PMID 24642531, 2014). "There were also no observed differences in ROCK2 gene level among various glioma subtypes." (PMID 35145081, 2022). "In the mRNAseq_693 data set of the Chinese Glioma Genome Atlas (CGGA), ROCK2 gene expression in the recurrent group was not significantly higher than that in the non-recurrent group." (PMID 35145081, 2022). "Unlike the results mentioned, we found that inhibition of ROCK2 decreased the ATM level in U87R and U251R cells, induced DSB and impaired DNA repair, suggesting that a novel mechanism was responsible for DSB repair in TMZ-R gliomas." (PMID 35145081, 2022).
Alzheimer disease (10 papers, 2019 to 2025). A progressive, neurodegenerative disease characterized by loss of function and death of nerve cells in several areas of the brain leading to loss of cognitive function such as memory and language. "Previous studies have demonstrated that administration of the ROCK2 inhibitor fasudil could prevent the reduction in dendritic arbour complexity and loss of dendritic spines in Alzheimer’s disease mice, which further consolidated our findings." (PMID 36417104, 2023). "Our results prove that the allosteric inhibition of the phosphorylation of APP by ROCK2 is a new, feasible option in the fight against Alzheimer’s disease." (PMID 37445593, 2023). "This causes the aberrant accumulation of several anaphase promoting complex/cyclosome-Cdh1 targets in the damaged areas of Alzheimer’s disease brains, including Rock2 and Cyclin B1." (PMID 36588673, 2022). "In this mini-review, we explore potential mechanisms by which ROCK2 mediates autophagy and actin dynamics and discuss how these pathways represent therapeutic avenues for Alzheimer’s disease." (PMID 33790742, 2021). "The selective inhibition of ROCK2 is particularly strong due to its high affinity for the enzyme, making it a valuable tool for studying ROCK2 function in research and in potential therapeutic applications, including for Alzheimer’s disease and the regulation of tau protein levels." (PMID 40143028, 2025). "For example, one paper suggests that targeting ROCK2, an actin-binding protein, may be therapeutic for Alzheimer’s disease by inducing autophagy, thereby reducing neurofibrillary tangles and enhancing plasticity of the spine, which is maintained in shape by actin." (PMID 36211457, 2022).
glaucoma (10 papers, 2020 to 2025). Increased pressure in the eyeball due to obstruction of the outflow of aqueous humor. "In the context of glaucoma therapy, the CasRx system predominantly focuses on the RNA‐level knockdown of aquaporin 1 (Aqp1), β2‐adrenergic receptor (Adrb2), and Rho‐associated kinase 1/2 (Rock1/Rock2)." (PMID 40536333, 2025). "Ripasudil (also known as K115) is currently in clinical use as a topical treatment for glaucoma and ocular hypertension and is a more selective inhibitor of ROCK2 with IC50 of 0.051 μM for ROCK1 and 0.019 μM for ROCK239." (PMID 40253509, 2025). "Next, we evaluated the therapeutic effect on glaucoma using the CasRx system to interfere with the expression of the Rock1 and Rock2 genes, as well as the Aqp1 and Adrb2 genes, on two simulated glaucoma model mice." (PMID 39080269, 2024). "Here, the authors show that AAV-delivered CasRx to reduce the expression of Rock1 and Rock2 as well as Aqp1 and Adrb2 can significantly reduce intraocular pressure, ultimately delaying glaucoma progression in mice." (PMID 39080269, 2024). "Using two different mouse models of glaucoma, we show that reducing the expression of Aqp1 and Adrb2 in the CB or Rock1 and Rock2 in the TM, significantly reduces IOP, protects retinal RGC cells and delays disease progression." (PMID 39080269, 2024). "Molecular docking, for instance, empowers researchers to predict the binding affinity and conformational preferences of potential therapeutic agents directed toward specific protein targets, as exemplified by the case of ROCK1 and ROCK2 in glaucoma." (PMID 37627868, 2023). "The expression of ROCK isoforms, ROCK1 and ROCK2, is recognized to occur in various ocular tissues and is also involved in the pathogenesis of several ocular diseases, including glaucoma, cataracts, corneal dysfunction, retinopathy and retinal dystrophy." (PMID 34298955, 2021). "And there is also study revealed that the ROCK1 and ROCK2 are expressed in the trabecular meshwork and ciliary muscle tissues of glaucoma patients." (PMID 32252692, 2020). "However, since the use of ROCK2 inhibitors to treat glaucoma has adverse side effects, such as conjunctival congestion and subconjunctival congestion, safer drugs are urgently needed." (PMID 36982538, 2023). "The molecular docking study was based on ligands with demonstrated biological action in the scientific literature (i.e., ripasudil and fasudil) and targeting key proteins (i.e., ROCK1 and ROCK2) identified as being involved in the modulation of glaucoma pathophysiological mechanisms." (PMID 37627868, 2023). "Consequently, ROCK2 inhibitors have potential therapeutic value for glaucoma, as well as other diseases such as erectile dysfunction, cardiovascular disease, central nervous system disease, fibrotic disease, inflammation, and diabetes." (PMID 36982538, 2023). "In addition, ROCK2 is abundantly expressed in the trabecular meshwork, making it an ideal target for glaucoma therapy." (PMID 36982538, 2023). "ROCK1 and ROCK2 were expressed in many organs including the retina, while excessive expression of ROCK1 and ROCK2 caused many diseases in the eye, such as diabetic retinopathy and glaucoma." (PMID 32252692, 2020). "Currently, marketed ROCK inhibitors approved for glaucoma treatment are Ripasudil (K-115; brand name: Glanatec) and netarsudil (AR-13324; brand name: Rhopressa), which target both ROCK1 and ROCK2." (PMID 38891764, 2024). "Recent studies indicated that ROCK2 plays a key role in smooth muscle contraction, and that ROCK2 inhibitors effectively control the symptoms of high intraocular pressure (IOP) in glaucoma patients." (PMID 36982538, 2023). "Studies have shown that ROCK2 inhibitors can lower IOP by modulating actin contractile fibers, thereby treating glaucoma." (PMID 36982538, 2023).
glaucoma (continued). "Small molecule ROCK2 inhibitors, such as Netarsudil and Ripasudil, are used in therapeutic settings to reduce IOP and treat glaucoma by reducing the resistance to AH outflow by relaxing the trabecular meshwork smooth muscle." (PMID 36982538, 2023). "Effects of a pan-ROCK-inhibitor, ripasudil (Rip), and a ROCK2 inhibitor, KD025 on dexamethasone (DEX)-treated human trabecular meshwork (HTM) cells as a model of steroid-induced glaucoma were investigated." (PMID 34770791, 2021). "Ripasudil, which was used for the treatment of glaucoma, was one kind of the inhibitor of ROCK1 and ROCK2, but whether ripasudil could relieve the LPS-induced inflammation and damage of RPE cells was not clear." (PMID 32252692, 2020). "However, ripasudil which was used as a drug for the treatment of glaucoma in Japan was also one of the inhibitors of ROCK1 and ROCK2." (PMID 32252692, 2020).
atherosclerosis (9 papers, 2013 to 2025). A disease characterized by the build-up of fatty material and calcium deposition in the arterial wall resulting in partial or complete occlusion of the arterial lumen. "MiR-532-5p alleviates ox-LDL-induced EC injury and ameliorates atherosclerosis by suppressing the expression of Rho-associated protein kinase 2 (ROCK2)." (PMID 40861271, 2025). "Since Rho/Rho kinase pathway has an important role for the pathogenesis of cardiovascular disease and atherosclerosis, the variants of ROCK2 may influence the body’s susceptibility to cardiovascular disease." (PMID 23326532, 2013). "Our study explored the function and mechanism of circ_0004104, miR-942-5p, and ROCK2 in atherosclerosis through in vitro and in vivo experiments, providing new biomarkers for the treatment of atherosclerosis." (PMID 36460954, 2022). "This study is the first to confirm the role of the circ_0004104/miR-942-5p/ ROCK2 axis in atherosclerosis, providing a new possibility for the treatment of atherosclerosis." (PMID 36460954, 2022). "Apart from that, related literature has confirmed that ROCK2 is boosted in atherosclerosis tissues and HUVECs cells, and restored the promotion effects of miR-135a-5p on ox-LDL-exposed HUVECs." (PMID 36460954, 2022). "And the expression of ROCK2 was negatively correlated with the level of miR-942-5p in Atherosclerosis patients." (PMID 36460954, 2022). "We conclude that targeting endothelial ROCK2 is potentially effective in attenuation of atherosclerosis." (PMID 30884801, 2019). "Collectively, these findings highlight the distinct and context-dependent roles of ROCK1 and ROCK2 in pulmonary hypertension, cardiac remodeling, fibrosis, and atherosclerosis, underscoring their potential as differential therapeutic targets in cardiovascular diseases." (PMID 41377066, 2025). "The circ_0004104/miR-942-5p/ROCK2 regulatory pathway might provide a new direction for the treatment of atherosclerosis." (PMID 36460954, 2022). "Our findings raise the possibility that targeting endothelial ROCK2 may be a feasible approach against atherosclerosis." (PMID 30884801, 2019). "However, the specific regulatory mechanisms of ROCK1 and ROCK2 in ameliorating graft atherosclerosis remain unclear." (PMID 28050227, 2016). "It was previously found that ROCK2 was obviously increased in HUVECs treated with ox-LDL and atherosclerosis patients." (PMID 36460954, 2022). "Analogously, our observations also indicated that ROCK2 was notably upregulated in atherosclerosis patients, and ox-LDL treatment boosted ROCK2 level in HUVECs in a concentration-dependent manner." (PMID 36460954, 2022). "But, the function of miR-942-5p, ROCK2, and circ_0004104 in atherosclerosis has not been reported." (PMID 36460954, 2022). "In a lysophosphatidic acid-induced model, lack of ROCK2, but not ROCK1, decreases the migration and adhesion of monocytes to endothelial cells, a critical initiating event in the early development of atherosclerosis." (PMID 41377066, 2025).
Cerebral ischemia (9 papers, 2019 to 2025). Restriction of arterial blood supply to the brain associated with insufficient oxygenation to support the metabolic requirements of the tissue. "In our current study, metformin inhibited Rock2 by downregulating lncRNA-H19 and then activated HO-1/Nrf2 to inhibit oxidative stress injury induced by cerebral ischemia." (PMID 31934270, 2019). "Our study illustrates that metformin prevents brain ischemia by accommodating I/R-induced oxidative stress via modulation of the lncRNA-H19/miR-148a-3p/Rock2 axis." (PMID 31934270, 2019). "Additionally, Slx-2119 (KD025) and SR3677, ROCK2-specific inhibitors, have also been shown to protect the cerebrovascular integrity in cerebral ischemia and reduce the production of amyloid-β in a mouse model of Alzheimer’s disease, respectively." (PMID 34834200, 2021). "ROCK1/ROCK2 inhibitors rescued the efficacy of BBB damage in several CNS diseases, including experimental autoimmune encephalomyelitis, cerebral ischemia, and intracerebral hemorrhage." (PMID 33548010, 2021). "Hence, the inhibition of ROCK1/ROCK2 has been proven to counteract BBB disruption resulting from brain injuries, such as cerebral ischemia, experimental autoimmune encephalomyelitis, and intracerebral hemorrhages." (PMID 34834200, 2021).